BCL2 (BCL2 apoptosis regulator)
Diseases named in the same sentence as BCL2 in open-access papers (continued):
Sharing a sentence is not in itself a finding about the gene and the disease.
lymphoma (continued). "Similarly, the double-expressor phenotype was also less prevalent in PT-DLBCL, while BCL6 rearrangements, double-expressor phenotype, and even double-hit lymphomas involving MYC and BCL6 or BCL2 are reported more frequently in western countries." (PMID 41244893, 2025). "In the transformation process in this case, lymphoma cells lost CD5 and BCL-2 and acquired CD10." (PMID 41357579, 2025). "Conversely, both partners of the HL/FL composite lymphoma were negative for the IGH::BCL2 translocation typical of classic FL." (PMID 40404986, 2025). "HGBCL lymphomas carry abnormal MYC and BCL2 via different mechanisms." (PMID 38918775, 2024). "The typical phenotype of BL (CD19 + /CD10 + /BCL2-/Ki67 > 95%/TdT-/CD34-/sIg +) with appropriate cytomorphology, demonstration of MYC-R alone, and simple karyotype differentiates MYC/BCL2 “double hit” lymphomas and lymphoblastic leukemia/lymphoma." (PMID 37530792, 2024). "In many of these lymphomas (up to 80% in some case series), the rearrangement of MYC together with that of BCL2 and/or BCL6 has been identified, a condition defined as “double-hit” (DH) or “triple-hit” (TH) lymphomas depending on the number of pathogenetically relevant lesions identified." (PMID 38534887, 2024). "Approximately 40% of cases are DPE lymphomas, being positive for both MYC and BCL2 proteins." (PMID 39684922, 2024). "The co-occurrence of MYC rearrangements with BCL2 and/or BCL6 rearrangements, known previously as “double-hit” or “triple-hit” lymphomas, now known as High-Grade B-Cell Lymphoma (HGBCL), is associated with very poor prognosis and resistance to conventional treatments." (PMID 40191738, 2024). "“Double hit” lymphomas with MYC and BCL2/BCL6 alterations confer a poor prognosis." (PMID 38534887, 2024). "There are rare cases where the translocation of MYC and BCL6 is present in the absence of BCL2 involvement (also defined as DH) and equally rare cases where all three translocations are present, a condition defined as “TH lymphomas”." (PMID 38534887, 2024). "MCL may also gain secondary BCL2, BCL6, and MYC rearrangements, as proposed in three of the previously reported quadruple hit lymphomas." (PMID 38914869, 2024). "This entity is characterized by the presence of MYC and BCL2 and/or BCL6 gene rearrangements and is referred to as HGBL-double-hit (DH)/-triple-hit (TH) and commonly referred to as double-hit (DHL) or triple-hit lymphoma (THL)." (PMID 39038016, 2024). "This was confirmed in a multicentre retrospective data collection study, which showed that MYC + BCL6 DH lymphoma does not represent high-risk lymphoma, while MYC + BCL2 DH lymphoma has particularly poor prognosis." (PMID 38965209, 2024). "Moreover, classifications that used to be under “Burkitt-like” lymphoma are now categorized as either high-grade B-cell lymphoma with MYC and BCL-2 and/or BCL-6 rearrangement, Burkitt-like lymphoma with 11q aberration, or simply high-grade B-cell lymphoma." (PMID 38535155, 2024). "Since our case had no rearrangement of MYC or BCL2, it was not consistent with “double-hit” lymphoma." (PMID 37884941, 2023). "A unique group among high-grade lymphomas, characterized by specific gene rearrangements, these lymphomas carry translocations in MYC together with one, or both, of the anti-apoptotic proto-oncogenes, BCL2 and BCL6." (PMID 37958379, 2023). "For example, in recent preclinical research, venetoclax, a BCL-2 inhibitor, enhanced in vitro antibody-dependent cellular phagocytosis of novel anti-CD20 and anti-CD19 antibodies via macrophages in BCL2-expressing double-hit lymphoma." (PMID 37508523, 2023). "Our results showed the coexpression of survivin and Bcl-2 positively correlated in the relapsed group and also in primary refractory DLBCL, which indicates an upregulation of anti-apoptotic and pro-survival mechanisms in the lymphoma cells." (PMID 37627134, 2023).
lymphoma (continued). "However, other lymphoma markers like CD3, cyclin D1, cytokeratin, epithelial membrane antigen (EMA), vimentin, B-cell lymphoma 2 (BCL2), CD117, CD34, desmin, and smooth muscle actin (SMA) were positive only in 1 case each." (PMID 36511607, 2023). "In addition, DLBCLs were added of which approximately 15–30% have a MYC translocation, which together with BCL2 and/or BCL6 translocation or amplification are known as ‘double’ or ‘triple’-hit lymphomas." (PMID 36792656, 2023). "Next, we explored the ability of BCL-2 and MCL-1 inhibitors to enhance PLK4 action in lymphoma." (PMID 36934096, 2023). "BCL-2, MCL-1, and BCL-XL are frequently over-expressed in lymphomas and leukaemias." (PMID 36342579, 2023). "As Bcl-2 was reported a FOXO10 target in lymphoma, we test whether CYP1B1 can affect the expression of Bcl-2 in CRC cells." (PMID 37059712, 2023). "Equally rare bona fide B-cell lymphoblastic leukemias/lymphomas with TdT expression and MYC translocations or, even rarer, MYC/BCL2 double hit have been mainly reported in the pediatric or adolescent setting and are molecularly different from DLBCL/HGBL-MYC/BCL2." (PMID 37190213, 2023). "We focused on BCL2 as this was the gene with the highest number of patients with TFA-BT NCVs in PCAWG and found that lymphoma patients with TFA-BT NCVs in the BCL2 promoter showed a marked allelic expression imbalance of BCL2 not observed in patients with other or no NCV in the BCL2 promoter." (PMID 36808133, 2023). "Taken together, M-100 exclusively induced apoptosis in murine lymphoma cells with elevated Myc levels as these cells failed to upregulate Bcl-2." (PMID 36068335, 2022). "Though double-hit-lymphomas and triple-hit-lymphomas are clinically aggressive neoplasms with poor prognosis, no significant clinical influence of the immunohistochemical assessment of c-Myc and BCL-2/BCL-6 was found in multivariate analyses." (PMID 36376836, 2022). "In support of this concept, the BCL2 inhibitor venetoclax potentiated the cytotoxic activity of IACS‐010759 in MYC/BCL2 DHL cells, while the Mcl‐1 inhibitor S63845 did so in MYC‐translocated, BCL2‐negative lymphoma cell lines." (PMID 34632715, 2022). "The lymphoma type-specific protein landscape of splenic CD19 + B cells of SLE-prone mice was analyzed by western blot for the expression of BCL2, that together with c-MYC defines the class of “double expressor” lymphomas, and for IRF4, an additional marker belonging to the ABC-DLBCL signature." (PMID 36503430, 2022). "In all, the use of BCL2 inhibitor alone may fail to achieve a satisfactory effect in lymphoma, but the combined use of BCL2 inhibitor and other DHL-BCL2 targeted drugs is promising, especially in BCL2 aberrant DLBCLs." (PMID 35303910, 2022). "Similarly, examination of a panel of lymphoma cell lines found that BFL-1+ lymphomas were less sensitive to BH3-mimetics targeting MCL-1 and BCL-2." (PMID 35900226, 2022). "For example, the human BCL-2 and c-MYC genes contain DNA sequences with the capacity to adopt non-B DNA structures that overlap with areas prone to breakage and chromosomal translocations found in lymphomas and leukemias." (PMID 40766048, 2022). "The lymphoma subtype at the time of transformation was DLBCL in 13 patients and high-grade B-cell lymphoma not otherwise specified in 5 patients (of which 1 patient was with MYC and BCL2 rearrangements, considering a double-hit lymphoma)." (PMID 36185179, 2022). "In BCL2‐negative lymphoma cells, instead, killing by IACS‐010759 was potentiated by the Mcl‐1 inhibitor S63845." (PMID 34632715, 2022). "Lymphomas with two oncogenic translocations other than MYC (e.g. concomitant Bcl-2 and Bcl-6 translocations without a MYC breakpoint) or other gene translocations associated with MYC translocations (e.g. CCND1 translocations) are not included in this category." (PMID 36618391, 2022). "Unlike standard Eμ-Myc lymphomas, BCL-2 expressing lymphomas are highly sensitive to the BCL-2 inhibitor venetoclax." (PMID 35961968, 2022).
lymphoma (continued). "Diffuse large B-cell lymphoma (DLBCL) with MYC alteration is classified as high-grade B-cell lymphoma with MYC and BCL2 and/or BCL6 rearrangements (double/triple-hit lymphoma; DHL/THL), DLBCL with MYC rearrangement (single-hit lymphoma; SHL) and DLBCL with MYC-cluster amplification (MCAD)." (PMID 36497332, 2022). "The expression of Bcl-2-targeting miRNAs was found to be decreased in MALT lymphomas and in diffuse large B-cell lymphoma (DLBCL) with higher expressions of Bcl-2 in stages 3 and 4 of both types of lymphomas." (PMID 36013278, 2022). "Additionally, three patients were diagnosed with double-hit lymphoma in the murinized group, carrying MYC and BCL2 or BCL6 translocations simultaneously, compared to four patients in the humanized group." (PMID 36552849, 2022). "This category of double- or triple-hit lymphomas only comprises translocations involving MYC and the two other genes; hence, lymphomas expressing MYC with BCL2 and/or BCL6 (according to immunochemical assessments) but that lack translocations are not encompassed by the definition." (PMID 35096627, 2021). "In lymphoid cancers, these same cell growth and survival pathways are disrupted and have uncontrolled activity; for example: in several human lymphomas, chromosomal translocations that activate MYC and BCL-2 are observed." (PMID 34440825, 2021). "DLBCL tumors that co-express both MYC and BCL2 proteins (regardless of genetic rearrangement) are referred to as double expressor lymphomas." (PMID 34282799, 2021). "Consistent with a role for translational activation in these aggressive lymphomas, we observe in a small cohort (n = 34) of MYC+/BCL2+ a clear correlation between MYC and BCL2 status and phosphorylation of ribosomal protein kinase p70S6K, an indicator of translation activation." (PMID 33562682, 2021). "cMYC and BCL2 simultaneous overexpression (double expressor lymphomas) comprehends a relevant inferior prognostic predictor in non-infected donors." (PMID 33996608, 2021). "Accordingly, various studies showed that targeting MCL-1, either through genetic- or BH3 peptide-based approaches, makes resistant cells significantly more sensitive to BCL-XL/BCL-2 inhibition, and abrogates growth of MCL-1-dependent cancers (e.g. AML and MYC-driven lymphoma)." (PMID 34515749, 2021). "Expression of MYC and BCL2 proteins is identified by immunohistochemistry (IHC) in some patients with DLBCL even when the chromosomal rearrangements of DH/TH lymphoma are not present." (PMID 34282799, 2021). "A third model, BCL2tracer mice, faithfully recapitulates the early stages of BCL2 deregulation, but does not advance to lymphomas." (PMID 34456919, 2021). "We confirmed that integrating B cell lymphoma-2 (Bcl-2) into CAR-T cells improved the proliferation ability of CAR-T cells in vitro and in vivo, which led to enhanced anti-tumor activity and prolonged survival in a mouse xenograft lymphoma model." (PMID 33429845, 2021). "Furthermore, the increased detection of genetic aberrations frequently observed in B-cell lymphomas, including BCL2, BCL6, IGH, and MALT1 translocations, should promote the development of lymphoma gene panels for BALF in the era of next-generation sequencing." (PMID 34873224, 2021). "On immunohistochemistry of the lymph node biopsy, CD20 was positive in follicles, CD5 was positive in interfollicular areas, and Bcl2 was negative, excluding lymphoma histologically." (PMID 34176492, 2021). "High-grade large B cell lymphomas with concurrent MYC and BCL2 (or BCL6) translocations, previously known as double-hit (DHL)/triple-hit lymphomas, represent a rare category of tumors that is now recognized as a separate provisional entity in the revised WHO classification." (PMID 34456919, 2021). "When considering only DLBCL-NOS, BCL2-positive lymphomas and double-expressors were more frequent in the non-GC subtype (68% vs. 33%; p < 0.001; and 2% vs. 21%; p = 0.005)." (PMID 34945856, 2021).
lymphoma (continued). "Using FISH, 4 separate assays (BCL2,-BA (break-apart), BCL6-BA, MYC-BA, MYC-IGH-F(fusion)) are needed to diagnose DH/TH lymphomas, while still missing those cases that carry a MYC-IGL translocation since no commercial probes are available for MYC-IGL fusion FISH." (PMID 34099699, 2021). "ABT-737 has already shown its efficacy in vitro on the apoptosis of carcinoma and AML cell lines, ex vivo on patient blasts, in vivo on a murine model of lymphoma, on a xenograft model of small cell lung cancer and our own mouse model of MRP8[NRASD12/BCL-2] AML post-MDS." (PMID 34638998, 2021). "Leukemia or lymphoma cells with mutated BAX, or BCL2 protein not primed for death, will not respond to venetoclax." (PMID 34576319, 2021). "Integrating anti-apoptotic molecule Bcl-2 into CAR design is a useful strategy for improving CAR-T cell proliferation in vitro and anti-tumor activity in vivo, which provides a potential approach for optimization of CAR-T cells against lymphoma in clinic." (PMID 33429845, 2021). "Interestingly, CR-1-31 B also shows strong activity against lymphoma cells with known MYC and/or BCL2 alterations that continue to represent a therapeutic challenge." (PMID 33562682, 2021). "High-grade B-cell lymphoma with MYC and BCL2 and/or BCL6 rearrangements, so called double-hit and triple-hit (DH/TH) lymphomas, are defined in the 2016 World Health Organization (WHO) classification as a new diagnostic category and includes a subset of tumors with DLBCL morphology." (PMID 34282799, 2021). "In the cases of DLBCLs, 3 triple expressor lymphoma cases and 7 double expressor lymphoma cases were identified by the co-expression of cMYC, BCL2, and BCL6 (cutoff points for expression of cMYC protein (≥ 40%), BCL2 protein (≥ 50%), BCL6 protein (≥ 50%))." (PMID 34737339, 2021). "In vitro studies on DH and DPE lymphoma-derived cell lines revealed that the survival of neoplastic cells seems to depend on BCL2 activity rather than that of MCL1, a protein with a pro-survival function." (PMID 31940809, 2020). "In addition, the patient's IHC test revealed co-expression of BCL-2 and MYC in lymphoma tissues, which indicated double-expressor lymphoma (DEL)." (PMID 32664092, 2020). "Based on these results and in the light of the current World Health Organization (WHO) classification of lymphoma the diagnosis was revised toward “high-grade B-cell lymphoma with MYC and BCL2 rearrangements, Burkitt morphology”, commonly referred to as “double-hit lymphoma”." (PMID 33339535, 2020). "The pattern of imbalances showing gains in 3q and trisomy 18 as well as homozygous loss in 9p21.3 (encompassing the region of CDKN2A/B) together with the lack of detectable CD10 in the presence of CD20 and BCL2 expression resembles other extra-nodal lymphoma." (PMID 33339535, 2020). "In terms of immunohistochemistry, expression of CD20 in lymphoma tissue could be detected in all patients, while only 32% (18/56) expressed CD10, 74% (34/46) Bcl-6, 65% (17/26) Bcl-2, and 66% (35/53) MUM1." (PMID 32160735, 2020). "Moreover, lymphomas that have a concomitant translocation of MYC and BCL-2 or BCL-6 represent high-grade B-cell lymphoma and are resistant to conventional R-CHOP chemotherapy." (PMID 32296035, 2020). "The prognosis for patients with r/r double-hit lymphoma (concurrent BCL2 and MYC translocations) is extremely poor without active salvage agents." (PMID 33317571, 2020). "Its clinical relevance was verified through its capacity to prevent important misclassification in low grade lymphomas and to retrieve clinically important characteristics in high grade lymphomas including the cell-of-origin signatures and the MYC and BCL2 expression levels." (PMID 32444689, 2020).
lymphoma (continued). "Whereas lymphomas with double expression of the proteins MYC and BCL2 are referred to as” double‐expressor lymphomas”.24, 25, 26, 27, 28, 29, 30 Patients with double gene rearrangements and double expression of MYC and BCL2 have an unfavorable prognosis and require intensified treatments." (PMID 31659781, 2020). "One of main limitations of the successful treatment of MYC/BCL2 DH lymphoma is lack of comprehensive understanding of disease pathogenesis and mechanisms of chemotherapeutic resistance, as well as knowledge of potential therapeutic targets." (PMID 32459397, 2020). "Of note, CD37−/−mice do not express increased amounts of Bcl2, meaning that lymphoma development is Bcl2 independent in this setting." (PMID 33333768, 2020). "We also incorporated molecular characterisation into our analysis to assess recognised subgroups distinct from the cell-of-origin subgroups: double-hit (rearrangements of MYC and BCL2 or BCL6, or both) and double-expressor lymphomas (high expression of MYC and BCL2 proteins)." (PMID 30948276, 2019). "They detected four cases of lymphoma with small CD10+ populations and high expression of Bcl-2." (PMID 31146399, 2019). "Notably, in a mouse model of DHL bearing primary tumor cells derived from lymphoma patients, combined treatment with XPO1 and BCL2 inhibitors blocks tumor progression, prevents brain metastasis, and extends host survival." (PMID 31752970, 2019). "We show that DZNep inhibits proliferation and induces apoptosis of these cell lines independent of the type of lymphoma, the EZH2 mutation status and the MYC, BCL2 and BCL6 rearrangement status." (PMID 31419226, 2019). "Specifically, all three lymphomas expressed CD20, CD79a and BCL2." (PMID 29793519, 2018). "Most Eμ‐MYC/Vav‐BFL1 mice also developed pre‐B lymphomas but a significant number (7 of 11 mice analysed) additionally developed CD19−B220+CD4+ progenitor cell lymphomas that have been described before for Eμ‐MYC/Eμ‐BCL2 mice." (PMID 29498802, 2018). "Furthermore, artesunate also potently induced apoptosis in WILL-2 and Oci-Ly-18 cells, representing “double hit lymphoma,” having aberrant overexpression of MYC and BCL2, and also in U2932, with a subclone with “double hit” aberrations." (PMID 29458389, 2018). "BCL-2/MYC DE was significantly more common among patients with BCL-2 translocation, as 10 out of a total of 15 BCL-2 -translocated lymphomas had DE and 24 out of a total of 111 without BCL-2 translocation were DE (p = 0.001)." (PMID 30287880, 2018). "Thus, there is a synergistic effect to accelerate lymphoma progression when both MYC and BCL2 are activated at the same time." (PMID 29674626, 2018). "It is important to differentiate DH/TH lymphomas from those with DP expression of MYC and BCL2." (PMID 30190794, 2018). "BCL2 and MYC are oncogenes commonly deregulated in lymphomas." (PMID 29747654, 2018). "For example, while one malignancy may have requirements for BCL-2, another might require BCL-X and/or BCL-W, highlighting the importance of using the right biomarkers to evaluate each lymphoma." (PMID 30671383, 2018). "Expression of CD20 in lymphoma tissue could be detected in all patients by immunohistochemical analyses, while only 9% expressed CD5, 55% CD10, 9% CD30, 18% CD79a, 9% CD138, 82% BCL2, 55% BCL6 and 36% MUM1." (PMID 30340554, 2018). "Therefore, combined targeting of BCL-2 and MCL-1 is a potential treatment strategy especially in aggressive lymphomas that are refractory to standard chemotherapy." (PMID 29269870, 2017). "Of note, only 8% of cases harbored a MYC rearrangement and no cases of MYC/BCL2 or MYC/BCL6 double-hit lymphoma were identified." (PMID 28212447, 2017).